UVRAG (UV radiation resistance associated)
Description:
Versatile protein that is involved in regulation of different cellular pathways implicated in membrane trafficking. Involved in regulation of the COPI-dependent retrograde transport from Golgi and the endoplasmic reticulum by associating with the NRZ complex; the function is dependent on its binding to phosphatidylinositol 3-phosphate (PtdIns(3)P). During autophagy acts as a regulatory subunit of the alternative PI3K complex II (PI3KC3-C2) that mediates formation of phosphatidylinositol 3-phosphate and is believed to be involved in maturation of autophagosomes and endocytosis. Activates lipid kinase activity of PIK3C3. Involved in the regulation of degradative endocytic trafficking and cytokinesis, and in regulation of ATG9A transport from the Golgi to the autophagosome; the functions seems to implicate its association with PI3KC3-C2. Involved in maturation of autophagosomes and degradative endocytic trafficking independently of BECN1 but depending on its association with a class C Vps complex (possibly the HOPS complex); the association is also proposed to promote autophagosome recruitment and activation of Rab7 and endosome-endosome fusion events. Enhances class C Vps complex (possibly HOPS complex) association with a SNARE complex and promotes fusogenic SNARE complex formation during late endocytic membrane fusion. In case of negative-strand RNA virus infection is required for efficient virus entry, promotes endocytic transport of virions and is implicated in a VAMP8-specific fusogenic SNARE complex assembly. Involved in maintaining chromosomal stability. Promotes DNA double-strand break (DSB) repair by association with DNA-dependent protein kinase complex DNA-PK and activating it in non-homologous end joining (NHEJ). Required for centrosome stability and proper chromosome segregation.
Synonyms: VPS38; DHTX; p63
Tractability: Small molecule: a structure with a bound ligand is known. PROTAC: ubiquitination databases record sites on it; its protein half-life has been measured.
Gene: Protein-coding gene on chromosome 11 (75,815,180 to 76,144,259, forward strand). Ensembl gene ENSG00000198382.
Subcellular location: Late endosome; Lysosome; Cytoplasmic vesicle, autophagosome; Early endosome; Endoplasmic reticulum; Midbody; Chromosome, centromere
Pathways (Reactome):
Disease: SARS-CoV-2 modulates autophagy; Translation of Replicase and Assembly of the Replication Transcription Complex
Autophagy: Macroautophagy
Gene Ontology:
Molecular function: protein binding; SNARE binding; SH3 domain binding
Biological process: autophagosome maturation; autophagy; centrosome cycle; DNA repair; double-strand break repair via classical nonhomologous end joining; maintenance of Golgi location; phosphatidylinositol-3-phosphate biosynthetic process; receptor catabolic process; regulation of autophagy; regulation of cytokinesis; regulation of protein serine/threonine kinase activity; retrograde vesicle-mediated transport, Golgi to endoplasmic reticulum; multivesicular body sorting pathway; positive regulation of autophagosome maturation; SNARE complex assembly; chromosome segregation; protein-containing complex organization; spindle organization; vesicle-mediated transport
Cellular component: autophagosome membrane; centrosome; DNA-dependent protein kinase complex; early endosome; endoplasmic reticulum; late endosome; lysosome; midbody; phosphatidylinositol 3-kinase complex, class III; cytoplasm; endoplasmic reticulum-Golgi intermediate compartment membrane; lytic vacuole; autophagosome; chromosome, centromeric region; cytoplasmic vesicle; phagocytic vesicle; protein-containing complex
Genetic constraint (gnomAD): Loss-of-function variants: 19 observed, 59.58 expected, observed/expected ratio (o/e) 0.32, 90% interval 0.22 to 0.47. The upper end of that interval is the gene's LOEUF score, 0.47, which puts it in group 2 of 6, group 1 being the genes least tolerant of losing a copy. Missense variants: 639 observed, 753.21 expected, observed/expected ratio (o/e) 0.85, 90% interval 0.79 to 0.91. Synonymous variants: 294 observed, 293.34 expected, observed/expected ratio (o/e) 1, 90% interval 0.91 to 1.1.
Homologues: Orthologues: chimpanzee UVRAG (99% identical), macaque UVRAG (97% identical), dog UVRAG (95% identical), guinea pig UVRAG (93% identical), rabbit UVRAG (91% identical), rat Uvrag (89% identical), mouse Uvrag (88% identical), pig UVRAG (88% identical), tropical clawed frog uvrag (71% identical), zebrafish uvrag (57% identical), Drosophila melanogaster Uvrag (21% identical), Caenorhabditis elegans Y34B4A.2 (11% identical), and 1 more.
Diseases named in the same sentence as UVRAG in open-access papers:
UVRAG is named in the same sentence as 36 diseases in open-access papers, as found by Europe PMC text mining. Sharing a sentence is not in itself a finding about the gene and the disease. The quoted sentences say what the papers report.
colon cancer (16 papers, 2010 to 2025). "The human colon cancer cell line HCT116 has a monoallelic mutation in the UVRAG gene that leads to significantly reduced expression levels of endogenous UVRAG and an anchorage‐independent cell growth." (PMID 36760166, 2023). "In human colon cancer, a single allelic mutated UV irradiation resistance-associated gene (UVRAG) is related to promoting autophagy and significantly inhibiting the proliferation of colon cancer cells." (PMID 37790849, 2023). "Confirming these results, knockdown of Beclin 1, the UV radiation resistance-associated gene (UVRAG) or ATG5 in human colon cancer cell lines enhanced ionizing radiation-induced DNA damage and cell death." (PMID 29112132, 2017). "UVRAG is found to be monoallelically mutated in human colon cancer, and UVRAG has been suggested to act by inhibiting the proliferation and tumorigenic activity of human colon cancer cells." (PMID 23110561, 2012). "In mammals, the Vps38p ortholog UVRAG was initially identified by partially complementing the UV sensitivity of xeroderma pigmentosum cells, and UVRAG participates in the development of a variety of human malignancies including breast and colon cancer." (PMID 29897620, 2018). "A key observation was that Beclin 1 and UVRAG can regulate centrosome stability in colon cancer cells." (PMID 24956373, 2014). "Recently, a novel beclin 1 binding protein, UVRAG, was found to positively regulate autophagy signaling pathway mediated by beclin 1 in colon cancer." (PMID 20230646, 2010). "UVRAG is frequently deleted (monoallelically) in colon cancers and overexpression leads to suppression of cell proliferation and tumorigenicity in human colon cancer cells." (PMID 20184741, 2010). "Furthermore, deletion in one copy of UV radiation resistance-associated gene (UVRAG), a regulator of beclin-1/PI3 K, promotes human colon cancer by inhibiting autophagy." (PMID 31428311, 2019). "In addition, ectopic expression of the BECN1 gene or UVRAG have both been shown to suppress the growth of xenografts of human colon cancer cell lines, suggesting that autophagy plays a tumor-suppressive role in tumorigenesis." (PMID 26965179, 2016). "UVRAG interacts with Beclin1-Bcl-2-VPS34 complex, suppresses the proliferation and tumorigenicity of human colon cancer cells." (PMID 34281589, 2021). "Studies have shown that UVRAG can act as a binding protein of BECN1 to mediate the activation of the BECN1-PI3KC3 complex to promote autophagy and inhibit the proliferation and tumorigenicity of colon cancer cells." (PMID 37790849, 2023). "Using yeast two-hybrid screening with SARS-CoV-2 ORF3a as a bait, we captured a novel protein-protein interaction with UVRAG, a key autophagy regulator that activates PI3KC3 complex to promote autophagosome maturation and suppresses the proliferation of human colon cancer cells." (PMID 34386498, 2021).
colorectal cancer (10 papers, 2014 to 2023). A primary or metastatic malignant neoplasm that affects the colon or rectum. "Monoallelic loss or mutation of UVRAG has been frequently reported in colon, gastric, or breast cancers, and mutations of UVRAG attenuate autophagy levels and promote tumorigenesis in colorectal cancer." (PMID 37108476, 2023). "miR-183 regulates autophagy and apoptosis in colorectal cancer through targeting of the ultraviolet radiation resistance-associated gene (UVRAG), a well-known regulator of autophagy that promotes autophagosome formation and maturation." (PMID 29089869, 2017). "It was found that in colorectal cancer, miR-183 regulates apoptosis in colorectal cancer cells by targeting UVRAG, which has been shown to have anti-apoptotic activity through interaction with Bax (BCL-2-associated X) during tumor treatment." (PMID 37372440, 2023). "For example, Up-regulation of miR-183 significantly inhibited cell autophagy and apoptosis through targeting of UVRAG in colorectal cancer." (PMID 29423086, 2018). "In line with previous studies, we confirmed that that miR-183 can affect apoptosis- and autophagy-mediated cell death in colorectal cancer cells through targeting UVRAG." (PMID 26717041, 2016). "To gain insight into the mechanism(s) by which tumor cell autophagy can confer treatment resistance, we examined the ability of Beclin 1 and/or its cofactor UVRAG to regulate the DNA damage response and centrosome number in colorectal cancer (CRC) cell lines." (PMID 24956373, 2014). "We found that UVRAG had a negative association with prognosis in colorectal cancer, which was mediated by its ability to enhance migration, stemness, and chemoradiotherapy resistance of cancer cells." (PMID 37173968, 2023). "In the HMF colorectal cancers, we discovered eight predictive gene deficiency models (MSH3, SMC2, SMC6, BMPR2, CLASP2, SRCAP, UBR5, and UVRAG) of monoallelic LOF with PR-AUC-E ranging from 0.21 (CLASP2) to 0.62 (MSH3) (AUROC ranging from 0.68 for SRCAP deficiency to 0.94 for MSH3 deficiency)." (PMID 36883553, 2023). "Therefore, the present study investigated the promoting effect of miR-183 on colorectal cancer progression, which was considered to be mediated by autophagy and apoptosis through targeting of UVRAG." (PMID 26717041, 2016). "Importantly, enhanced expression of UVRAG alleviates miR-183-mediated repression of autophagy and induces apoptosis in colorectal cancer cells, confirming the functional importance of this target." (PMID 26717041, 2016). "In summary, we found that Beclin 1 and UVRAG regulate the DNA damage/repair response that may utilize NHEJ to repair DSBs in irradiated colorectal cancer cells." (PMID 24956373, 2014). "The deregulation of autophagy regulators has been observed in different types of cancers, such as the monoallelic deletion of Beclin-1 gene in human breast, ovarian and prostate cancers; the frameshift mutations of UVRAG and other ATG genes in gastric and colorectal cancers." (PMID 25026290, 2014).
breast carcinoma (7 papers, 2015 to 2023). "Autophagy is required for the hemostasis of cell to prevent tumorigenesis, and absence of autophagy master genes, such as Beclin-1, ATG5, and UVRAG, has been reported in multiple cancers including breast cancer lung cancer." (PMID 34475961, 2021). "In breast cancer, Beclin-1 cooperates with a member of PI3KC3 complex, UVRAG, to recruit E-cadherin and other components of the E-cadherin/catenin complex to the membrane of breast cancer cells." (PMID 35884904, 2022). "In both breast cancer cell types, Bg induced the expression of other strictly related proteins such as PI3KIII, UVRAG, and AMBRA which cooperate to the autophagosome formation." (PMID 26148846, 2015). "Interestingly we evidenced the appearance of an authophagic phenotype by Bg treatment as revealed by fluorescence microscopy of LC3-GFP in breast cancer cells together with an increase of different key hallmarks of the autophagic process such as Beclin 1, PI3K III, UVRAG and Ambra1." (PMID 26148846, 2015). "Whereas the origin of the autophagy disruption is still unknown, mutations or loss of heterozygosity-dependent autophagy gene silencing (LC3, ATGs, UVRAG, BECN-1) have been reported in many different cancers, such as colorectal, gastric carcinoma or breast cancers." (PMID 26474850, 2015).
gastric cancer (4 papers, 2015 to 2022). A primary or metastatic malignant neoplasm involving the stomach. "The mutation was reported in Beclin1 binding protein UVRAG (UV irradiation Resistance-Associated Gene) which also regulate autophagy in human gastric cancer." (PMID 30274346, 2018).
glioma (4 papers, 2020 to 2025). A benign or malignant brain and spinal cord tumor that arises from glial cells (astrocytes, oligodendrocytes, ependymal cells). "The low ULK2, UVRAG, and miR-374 expression group exhibited significantly poor overall survival in glioma, while miR-21 over-expression indicated a poor prognosis in glioma patients, validating it in our population." (PMID 39348350, 2024). "Moreover, mIDH1 glioma cells showed upregulation of UVRAG, MST4, and pATG4b53." (PMID 40964044, 2025). "Furthermore, when we treated two different mIDH1 mouse glioma cell models with α-ketoglutarate (α-KG), we found that the mIDH1 cells reverted the expression patterns showing significant reduction in several key autophagy regulators including pATG4b, UVRAG, ATG7, and ATG9b." (PMID 40964044, 2025). "While correlation analysis identified a strong positive correlation between ULK2 and UVRAG, PTEN, miR-7, and miR-100 in low-grade glioma, unveiling distinctive molecular signatures unique to our study." (PMID 39348350, 2024). "AKT positively correlated with LC3, PI3K, PTEN, ULK1, VPS34, mTOR, Beclin1, UVRAG, miR-7, miR-30, miR-204, miR-374, miR-126 and miR-21 weakly correlated with AKT and miR-30 in high-grade glioma, providing further insights into the autophagy pathway within our population." (PMID 39348350, 2024). "In 39 glioma cases, we assessed the protein expression of autophagy markers LC3B, SQSTM1/p62, and DRAM by immunohistochemistry (IHC) and the mRNA expression of the autophagy genes PTEN, PI3K, AKT, mTOR, ULK1, ULK2, UVRAG, Beclin 1, and VPS34 using RT-qPCR." (PMID 38203743, 2024). "However, Wang H reported that upregulated expression of miR-33a was correlated with poor prognosis of GBM patients and enhanced self-renewal of glioma-initiating cells via activation of the PKA and NOTCH pathways by targeting PDE8A and UVRAG." (PMID 32206036, 2020). "In grade 3 gliomas, a significant, strong, positive correlation was observed between PI3K and mTOR, ULK2, UVRAG; mTOR and PTEN; PTEN and m-TOR, ULK 2, UVRAG; mTOR and PI3K, PTEN; ULK1 and ULK2, UVRAG; ULK 2 and PI3K, PTEN, ULK 1, UVRAG, VPS34; UVRAG and PI3K, PTEN, ULK1, ULK2, VPS34." (PMID 38203743, 2024).
COVID-19 (3 papers, 2021 to 2024). A disease caused by infection with severe acute respiratory syndrome coronavirus 2. "It was found that transcript levels of key factors promoting autophagy, i.e. ULK-1, ATG5, UVRAG, AMBRA, PIK3C3, and LC3, are significantly reduced in mononuclear cells of COVID-19 patients compared to healthy controls, and the phenomenon was more pronounced in severe COVID-19 patients." (PMID 33692788, 2021).
prostate carcinoma (3 papers, 2014 to 2019). A carcinoma that arises from epithelial cells of the prostate gland. "The allelic loss of proteins interacting with Beclin-1, such as UV radiation resistance-associated gene protein (UVRAG) and Bax-interacting factor-1, is also common in breast, gastric, colon, bladder, and prostate cancer." (PMID 31569540, 2019).
liver fibrosis (2 papers, 2022). "Briefly, lncRNA SNHG1 silencing was observed to downregulate SMURF1 by upregulating miR-15a, diminishing ubiquitination of UVRAG to activate ATG5/Wnt5a axis, which accelerated HLC differentiation from BMSCs and repressed liver fibrosis to inhibit cirrhosis." (PMID 35194023, 2022). "Moreover, our data revealed that miR-15a targeted SMURF1, which enhanced ubiquitination of UVRAG, to promote BMSCs to differentiate to HLC in vitro and repress liver fibrosis in mice with cirrhosis." (PMID 35194023, 2022).
autoimmune disease (1 paper, 2024). A disorder resulting from loss of function or tissue destruction of an organ or multiple organs, arising from humoral or cellular immune responses of the individual to their own tissue constituents. "It has also been reported that UVRAG dysfunction plays an important role in autoimmune diseases by affecting the process of autophagy." (PMID 39660984, 2024).
Chagas disease (1 paper, 2021). A parasitic infection caused by Trypanosoma cruzi. "To address this, here we investigated the role of the variant subunits VPS38/UVRAG (complex II, endocytosis) and ATG14 (complex I, autophagy) in the biogenesis of the yolk organelles in the insect vector of Chagas Disease Rhodnius prolixus." (PMID 34492013, 2021).
Cirrhosis (1 paper, 2022). A chronic disorder of the liver in which liver tissue becomes scarred and is partially replaced by regenerative nodules and fibrotic tissue resulting in loss of liver function. "Conclusively, lncRNA SNHG1 silencing might facilitate HLC differentiation from mouse BMSCs and alleviate cirrhosis via the miR-15a/SMURF1/UVRAG/ATG5/Wnt5a axis." (PMID 35194023, 2022). "Therefore, our work was designed to figure out impacts of lncRNA SNHG1 on cirrhosis by orchestrating HLC differentiation of BMSCs via miR-15a/SMURF1/UVRAG/ATG5/Wnt5a axis." (PMID 35194023, 2022). "Another critical finding in our study was that overexpressed UVRAG promoted ATG5/Wnt5a activation to decrease HLC differentiation of BMSCs, thus alleviating cirrhosis." (PMID 35194023, 2022).
colitis (1 paper, 2021). Inflammation of the colon. "Another study showed that mutant mice that inducibly express UVRAG, a tumor suppressor gene involved in autophagy process, display increased inflammatory response in colitis-associated cancer development and promote spontaneous tumorigenesis associated to age-related autophagy suppression." (PMID 33923277, 2021).
dysplasia (1 paper, 2016). A usually neoplastic transformation of the cell, associated with altered architectural tissue patterns. "In fact, UVRAG loss resembles an early-onset age-associated dysplasia that is normally observed in old (30-60 days) flies and involves the simultaneous activation of both JNK and STAT signaling." (PMID 26921396, 2016).
epilepsy (1 paper, 2025). A brain disorder characterized by episodes of abnormally increased neuronal discharge resulting in transient episodes of sensory or motor neurological dysfunction, or psychic dysfunction. "Notably, we found eight proteins shared by stroke and epilepsy (e.g., SH3BGRL3, PTPMT1), nine shared by epilepsy and VaD (e.g., DOCK7, BCAN), and ten by stroke and VaD (e.g., MTHFR, UVRAG), suggesting common pathogenic axes like inflammation and cellular stress." (PMID 40624693, 2025).
head and neck squamous cell carcinoma (1 paper, 2014). A squamous cell carcinoma that arises from any of the following anatomic sites: lip and oral cavity, nasal cavity, paranasal sinuses, pharynx, larynx, and salivary glands. "MiR-630 was also found to be upregulated in head and neck squamous cell carcinoma after cisplatin treatment and can modulate the protein expression of ATG5, ATG6/BECN1, ATG10, ATG12, ATG16L1 and UVRAG." (PMID 24621930, 2014).
hepatocellular carcinoma (1 paper, 2023). A malignant tumor that arises from hepatocytes. "Moreover, UVRAG ubiquitination, associated with phosphorylation status, results in a significant blockade of hepatocellular carcinoma (HCC) growth in vitro and in vivo." (PMID 36831455, 2023).
lymphoma (1 paper, 2019). A malignant (clonal) proliferation of B- lymphocytes or T- lymphocytes which involves the lymph nodes, bone marrow and/or extranodal sites. "Although knockout of UVRAG is embryonic lethal in mice, the inactivation of UVRAG by the expression of UVRAGFS causes the premature onset of age-related neoplasia, particularly spontaneous lymphoma, in iUVRAGFS mice, independently of its role in inflammasome regulation." (PMID 31831743, 2019).